CFHR1 (complement factor H related 1)
Description:
Involved in complement regulation. The dimerized forms have avidity for tissue-bound complement fragments and efficiently compete with the physiological complement inhibitor CFH. Can associate with lipoproteins and may play a role in lipid metabolism.
Synonyms: FHR-1; FHL-1; CFHL; CFHL1; CFHL1P; CFHR1P; FHR1; HFL1; HFL2; H36-1; H36-2; H36
Tractability: Antibody: its Gene Ontology location is reachable by antibodies, with high confidence; UniProt places it where antibodies can reach, with medium confidence; UniProt predicts a signal peptide or a membrane-spanning region.
Gene: Protein-coding gene on chromosome 1 (196,819,314 to 196,837,159, forward strand). Ensembl gene ENSG00000244414.
Subcellular location: Secreted
Subcellular location (Human Protein Atlas): Vesicles; Predicted to be secreted
Pathways (Reactome):
Immune System: Regulation of Complement cascade
Gene Ontology:
Molecular function: identical protein binding; protein binding; complement component C3b binding
Biological process: positive regulation of complement activation; complement activation
Cellular component: blood microparticle; protein-containing complex; extracellular region
Genetic constraint (gnomAD): Loss-of-function variants: 21 observed, 25.04 expected, observed/expected ratio (o/e) 0.84, 90% interval 0.59 to 1.21. The upper end of that interval is the gene's LOEUF score, 1.21, which puts it in group 5 of 6, group 1 being the genes least tolerant of losing a copy. Missense variants: 238 observed, 330.79 expected, observed/expected ratio (o/e) 0.72, 90% interval 0.65 to 0.8. Synonymous variants: 89 observed, 112.31 expected, observed/expected ratio (o/e) 0.79, 90% interval 0.67 to 0.94.
Homologues: Orthologues: chimpanzee CFHR1 (81% identical), mouse Cfhr1 (59% identical), rat Cfhr1 (52% identical). Paralogues in human: CFH (72% identical), CFHR2 (71% identical), CFHR5 (55% identical), CFHR3 (36% identical), CFHR4 (31% identical), F13B (24% identical), CSMD3 (20% identical), CSMD1 (20% identical), SVEP1 (20% identical), CSMD2 (19% identical), PAPPA (18% identical), PAPPA2 (18% identical), and 27 more.
Diseases named in the same sentence as CFHR1 in open-access papers:
CFHR1 is named in the same sentence as 95 diseases in open-access papers, as found by Europe PMC text mining. Sharing a sentence is not in itself a finding about the gene and the disease. The quoted sentences say what the papers report.
atypical hemolytic-uremic syndrome (20 papers, 2011 to 2025). A rare, genetic thrombotic microangiopathy due to dysregulation of the alternative complement pathway and characterized by the triad of hemolytic anemia, thrombocytopenia, and acute renal dysfunction. "Variations in the CFH and CFHR1 genes have been studied for disease susceptibilities, including age-related macular degeneration, dense deposit disease, atypical hemolytic-uremic syndrome, and systemic lupus erythematosus (SLE)." (PMID 23894628, 2013). "Additionally, gene copy number changes in the CFHR1–5 region, affecting factor H function, have been associated with both atypical hemolytic uremic syndrome (aHUS) and C3G, playing an important diagnostic and prognostic role." (PMID 41155921, 2025). "Recent data demonstrate that increased CFHR1 is found in active IgA nephropathy, ANCA vasculitis, C3 glomerulonephritis, and atypical hemolytic uremic syndrome and might be associated with CFHR1 gene variants." (PMID 40283082, 2025). "For example, while CFHR1 expression confers risk for AMD, it is protective against atypical hemolytic uremic syndrome." (PMID 27668132, 2016). "The combined deletion of CFHR3 and CFHR1 that is protective in AMD is associated with an increased risk for atypical hemolytic uremic syndrome." (PMID 21850184, 2011). "The combined deletion of CFHR1 and CFHR4 has only been described as an increased risk for the atypical hemolytic uremic syndrome." (PMID 21850184, 2011). "While defective CFHR5 may contribute to atypical hemolytic uremic syndrome, CFHR1 has been shown to be downregulated in tissue from LUAD tumors compared to healthy adjacent tissue." (PMID 36544145, 2022). "Deletion of the CFHR-1 and CFHR-3 genes decreases the risk of immunoglobulin A nephropathy and AMD (23, –, 26) but predisposes to systemic lupus erythematosus and atypical hemolytic uremic syndrome (aHUS), a form of thrombotic micoangiopathy leading to end-stage renal failure." (PMID 28637873, 2017). "This deletion, with breakpoints within the last three exons of CFH and CFHR1, results in a hybrid CFH-CFHR1 protein, which leads to atypical hemolytic uremic syndrome as a result of defective recognition function." (PMID 22022419, 2011).
age-related macular degeneration (18 papers, 2012 to 2025). Age-related loss of vision in the central portion of the retina (macula), secondary to retinal degeneration. "For example, CFHR3 and CFHR1 are associated with age-related macular degeneration and systemic lupus erythematous." (PMID 23594316, 2013). "This 71-kb deletion spans the entire CFHR1 and CFHR3 locus that is associated with an increased risk of the hemolytic uremic syndrome and a decreased risk of age-related macular degeneration." (PMID 33420067, 2021). "For example, a common CFH haplotype with deletion of CFHR1 and CFHR3 genes associated with lower risk of age-related macular degeneration was identified using the GStream CNV calls." (PMID 23844243, 2013). "The absence of both copies of CFHR3 and CFHR1 is also associated with a lower risk of age-related macular degeneration (AMD) and IgA nephropathy, and a higher risk of atypical haemolytic uremic syndrome (aHUS) and systemic lupus erythematosus (SLE)." (PMID 34211499, 2021).
IgA nephropathy (13 papers, 2017 to 2025). "Deleting complement factor H-related genes 1 and 3 (CFHR1/3) is protective against IgA nephropathy, while increased plasma levels of FHR-1/Factor H and FHR-5 (antagonists of FH) are associated with progressive kidney disease." (PMID 38895123, 2024). "A single deletion in both CFHR1 and CFHR3 confers a 30% reduction in the risk of IgA nephropathy, and a meta-analysis with risk-score model including Asian, European, and African population evaluated five susceptibility loci of three MHC, one CHF and one HORMAD2." (PMID 34354705, 2021). "Previous studies have also revealed that CFHR1 may play an important role in acute myelogenous leukemia, IgA nephropathy, and chronic central serous chorioretinopathy." (PMID 32704452, 2020). "A genome-wide association study of IgA nephropathy identified three independent loci in the major histocompatibility complex (MHC) and a common deletion in CFHR1 and CFHR3 that reached genome-wide significance, emphasizing the crucial role of complement activation in the disease." (PMID 28642464, 2017). "Additionally, the genes CFHR1 and CFHR3, associated with the complement factor H family, have been identified as playing a role in inducing cellular senescence in the tubular cells of kidney allografts in patients with IgA nephropathy." (PMID 39602449, 2024). "The deletion of the CFHR3 and CFHR1 genes is protective in IgA nephropathy presumably via the lack of FH competitors (FHR-1, FHR-3) on the surfaces, leading to more effective inhibition of complement activation by FH." (PMID 38410512, 2024).
systemic lupus erythematosus (8 papers, 2011 to 2024). An autoimmune multi-organ disease typically associated with vasculopathy and autoantibody production. "The absence of an association of CFHR3-1Δ with renal disorder in lupus suggests that CFHR3 and CFHR1 play a different role from CFH in the pathogenesis of lupus, although further studies are required to validate the lack of association between the CFHR3-1Δ deletion and renal disorder in SLE." (PMID 21637784, 2011).
hemolytic-uremic syndrome (6 papers, 2011 to 2025). Acute kidney injury associated with microangiopathic hemolytic anemia and thrombocytopenia. "Paradoxically, loss-of-function mutation or deletion of complement-protective CFHR1/3 (protective for AMD) is actually pathogenic in other conditions such as C3 glomerulopathy and hemolytic uremic syndrome (HSU)." (PMID 27239555, 2016). "Expression of SLC4A3, which regulates cardiac potential, and CFHR1, associated with an atypical hemolytic-uremic syndrome, were also ruled out." (PMID 40676628, 2025).
atherosclerosis (5 papers, 2019 to 2026). A disease characterized by the build-up of fatty material and calcium deposition in the arterial wall resulting in partial or complete occlusion of the arterial lumen. "The most important modulators of CFH binding to MDA-epitopes – the CFH variant Tyr402His and the deletion of CFHR3&CFHR1 genes – are frequent in the population and affect the development of the two most common diseases, atherosclerosis and AMD." (PMID 36248824, 2022). "Moreover, the concentration of FHR1 is higher, whereas CFHR1 gene deletion frequency is significantly lower in patients with atherosclerosis in comparison to healthy controls." (PMID 41583528, 2026). "Deletion of CFHR3&CFHR1 genes offers protection in both of them, while Tyr402His is deleterious in AMD and possibly atherosclerosis, highlighting CFH’s importance in homeostatic responses." (PMID 36248824, 2022).
thrombotic microangiopathy (4 papers, 2020 to 2024). The syndromes of microangiopathic hemolytic anemia, thrombocytopenia, and variable signs of organ impairment, due to platelet aggregation in the microcirculation. "Of note, a case report demonstrated that the pathogenic nature of IgG4 autoantibodies directed against CFH could trigger the C’-mediated thrombotic microangiopathy in a patient carrying a genetic predisposition for homozygote CFHR1/4 gene deletion." (PMID 36834989, 2023). "One reported case showed that shiga toxin was a potential trigger of CFHR1 deletion-related thrombotic microangiopathy." (PMID 32636836, 2020).
bladder cancer (3 papers, 2020 to 2024). "Electrochemical ELISA-based immunosensors are commonly used for the detection of protein biomarkers in bladder cancer, such as nuclear mitotic apparatus protein 1 (NUMA1) and complement factor H-related 1 (CFHR1)." (PMID 39771612, 2024). "Recently, a novel fluidic-based DPV ELISA platform for estimating the protein markers of bladder cancer (nuclear mitotic apparatus protein 1 (NUMA1) and complement factor H-related 1 (CFHR1)) was proposed." (PMID 32585936, 2020).
C3 glomerulopathy (3 papers, 2021 to 2025). "FH autoantibodies are reported in 8-25% of aHUS patients in different cohorts and are strongly associated with homozygous deletion of the CFHR1 gene, but are more rarely reported in patients with C3 glomerulopathies including dense deposit disease." (PMID 33986750, 2021).
Hypertension (3 papers, 2012 to 2019). The presence of chronic increased pressure in the systemic arterial system. "Loss of CFHR1 was important for progression of hypertension, but loss this gene may be responsible for advancement of CAD." (PMID 31881747, 2019). "Therefore, the rs7542235 (CFHR1–3Δ) may contribute to hypertension risk by increasing inflammatory response, and rs2274700 (A473A) is likely to be in LD with other genetic variants that affect expression of CFH or binding capacity of CFH with CRP." (PMID 22848687, 2012).
membranoproliferative glomerulonephritis (3 papers, 2012 to 2024). Inflammation of the glomeruli characterized by deposits at the intraglomerular mesangium, resulting in thickening of the glomerular basement membrane, activation of complement, and impaired kidney function secondary to damaged glomeruli. "For example, studies of the RCA alpha block encompassing CFH and CFHR1-5 genes have shown associations with AMD, aHUS, Membranoproliferative Glomerulonephritis and SLE." (PMID 22558131, 2012).
acute kidney injury (2 papers, 2020 to 2022). Sudden and sustained deterioration of the kidney function characterized by decreased glomerular filtration rate, increased serum creatinine or oliguria. "Here, a Cfhr1 knockout mouse was generated for investigating AP in sepsis and sepsis-induced acute kidney injury (AKI)." (PMID 32636836, 2020).
autoimmune (2 papers, 2015 to 2024). "In this study, we aimed to solve why a deficiency of one molecule (CFHR1) predisposes to autoimmunity against another, highly homologous molecule (CFH) in aHUS." (PMID 25659429, 2015). "Therefore, we do not suggest that all microbial molecules that bind to CFH domain 20 could lead to autoimmunity in CFHR1-deficient individuals." (PMID 25659429, 2015). "However, it is possible that some of the microbial molecules that bind to the domain do not mask the autoantigenic loop, thereby leading to the risk of autoimmunity in the absence of CFHR1." (PMID 25659429, 2015).
endothelial dysfunction (2 papers, 2024 to 2025). In vascular diseases, endothelial dysfunction is a systemic pathological state of the endothelium (the inner lining of blood vessels) and can be broadly defined as an imbalance between vasodilating and vasoconstricting substances produced by (or acting on) the endothelium. "We hypothesize that our patient's WT1 mutations resulted in a podocytopathy that led to endothelial dysfunction, which, combined in one patient with CFHR1,4, culminated in the development of aHUS." (PMID 39445256, 2024).
glaucoma (2 papers, 2023 to 2024). Increased pressure in the eyeball due to obstruction of the outflow of aqueous humor. "However, eight proteins (C6, C8G, CFH, C3, CFHR1, CFI, CLU, and SERPING1) were significantly downregulated in Caucasian glaucoma subjects." (PMID 37763167, 2023).
Nephropathy (2 papers, 2020 to 2026). A nonspecific term referring to disease or damage of the kidneys. "Human CFHR1 deletion was associated with nephropathy and kidney injury can be induced by complement overactivation." (PMID 32636836, 2020).
autoimmune disease (1 paper, 2015). A disorder resulting from loss of function or tissue destruction of an organ or multiple organs, arising from humoral or cellular immune responses of the individual to their own tissue constituents. "Autoimmune aHUS is an unusual autoimmune disease because it is associated with a deficiency of a protein (CFHR1) homologous to the autoantigen (CFH)." (PMID 25659429, 2015). "Thus, on the basis of the new data, we propose a novel explanation for the association of CFHR1 deficiency with the autoimmune disease." (PMID 25659429, 2015).
cholangiocarcinoma (1 paper, 2022). A carcinoma that arises from the intrahepatic biliary tree (intrahepatic cholangiocarcinoma) or from the junction, or adjacent to the junction, of the right and left hepatic ducts (hilar cholangiocarcinoma). "Finally, we observed CFHR1 in the PPI network, which is a member of the CFHR gene family; therefore, we performed the differential analysis of the CFHR gene family in cholangiocarcinoma." (PMID 36213819, 2022).
complement deficiencies (1 paper, 2025). "Next-generation sequencing, covering approximately 5,000 genes, including those associated with familial HLH, and wide range of IEI and complement deficiencies (such as C3, CFB, CFH, CFHR1, CFHR3, CFHR5, CFI) and MLPA analysis for CFHR1/CFHR3 deletions, was performed." (PMID 40995360, 2025).
glioblastoma (1 paper, 2022). The most malignant astrocytic tumor (WHO grade IV). "It was reported that human H2 glioblastoma cells synthesize high levels of CFHR1, so the protein can be hypothesized to be involved in one of the mechanisms used to avoid cellular death, typical of tumors." (PMID 35216175, 2022).
macular degeneration (1 paper, 2016). Loss of vision in the central portion of the retina (macula), secondary to retinal degeneration. "Interestingly, seven genes associated with macular degeneration (CFH, C3, C2, CFHR5, CFB and CFHR4, CFHR1) also form a statistically significant module in liver (p value < 10−26, z score = 10.85)." (PMID 27748412, 2016).
Obesity (1 paper, 2020). Accumulation of substantial excess body fat. "They complement regulation associated with lipoproteins and lipid metabolism and adipogenesis, encompassing CFHR1, CFHR3, and BMPR2 protein–protein interactions, given marked obesity is a common finding in PWS." (PMID 32384786, 2020).
preeclampsia (1 paper, 2025). Preeclampsia is a hypertensive disorder of pregnancy that is characterized by new-onset hypertension with proteinuria presenting after 20 weeks of gestation, and depending on mild or severe forms may initially present with severe headache, visual disturbances, and hyperreflexia. "These patients have higher complement mutation frequency, including rare germline mutations in the alternative CS pathway (CFHR1, CFHR3, CFI, CFB, and CD46) than women with preeclampsia, having similar rates of variants as the control population." (PMID 40904461, 2025).
prostate carcinoma (1 paper, 2012). A carcinoma that arises from epithelial cells of the prostate gland. "The finding of CFH and CFHR1 up-regulation in PP adipose tissue of subjects with prostate cancer suggests increased inhibitory modulation of the complement activity in prostate tumor cells and evasion to attack." (PMID 23009291, 2012).
rheumatic diseases (1 paper, 2012). "Since in aHUS an association was reported between the presence of FH-autoantibodies and homozygous deletions of the gene encoding CFHR1 and CFHR3, we now also analyzed whether there is such an association in rheumatic diseases." (PMID 22894814, 2012).
senile cataract (1 paper, 2024). A cataract with no obvious cause occurring in persons over 50 years old. "After correction for multiple testing, we identified two potential causal genes, namely KHK associated with senile cataract (OR = 1.089, 95%CI (1.035–1.145), FDR.p = 1.44 × 10−3) and CFHR1 (OR = 3.049, 95%CI (2.636–3.527), FDR.p = 7.04 × 10−50)." (PMID 39408566, 2024).
Sepsis (1 paper, 2020). Sepsis is defined as life-threatening organ dysfunction caused by a dysregulated host response to infection. "We found that murine FHR-1 homolog (FHR-E) deficiency enhanced lipopolysaccharide (LPS)-induced AP activation both in vitro and in vivo and that Cfhr1 knockout mice exhibited more severe sepsis and AKI in response to LPS challenge." (PMID 32636836, 2020). "Our results revealed that Cfhr1 knockout mice challenged with LPS served as a good model to study the intricate network of complement, inflammation, and coagulation in sepsis and AKI." (PMID 32636836, 2020). "In this study, Cfhr1 was deleted on C57BL/6 mouse to study the function of FHR-E on AP and the effect of FHR-E deficiency on LPS-induced sepsis." (PMID 32636836, 2020).
tumor (11 papers, 2012 to 2025). "We also identified 44 lost segments, which harbored tumor suppressors including CDKN2A (9p21.3), ADAM3A (8p11.22), and CFHR1/CFHR4 (1q31.3)." (PMID 34070941, 2021). "Further lasso regression analysis identified seven potential prognostic markers (IL27, CD1D, NCOA6, CTSE, FCGRT, CFHR1, and APOA2) of robustness, most of which are related to tumor development." (PMID 32518711, 2020). "The protein CFHR1 may, thus, serve as a potential tumor marker for TC, and the lack of other appropriate biomarkers for TC may compensate for this marker’s lower sensitivity and specificity." (PMID 32704452, 2020).